IGF1 (insulin like growth factor 1)
Diseases named in the same sentence as IGF1 in open-access papers (continued):
Sharing a sentence is not in itself a finding about the gene and the disease.
Insulin resistance (continued). "This interplay likely stems from shared pathophysiological mechanisms, including insulin resistance (IR), chronic inflammation, altered myokine secretion, imbalances of hormones, including growth hormone and IGF-1, vitamin D deficiency, and physical inactivity." (PMID 40852370, 2025). "Low IGF-1 is linked to insulin resistance and related metabolic disorders." (PMID 40538800, 2025). "Despite these benefits, GH can cause side effects like edema and insulin resistance, while IGF-1 may lead to hypoglycemia." (PMID 39529965, 2024). "Moreover, the loss of skeletal mass contributes to the development of insulin resistance, subsequently increasing insulin-like growth factor-1 (IGF-1) levels." (PMID 39001378, 2024). "Cigarette smoking increases both the risk for insulin resistance and amyloid‐β (Aβ) aggregation, and impaired brain insulin/insulin‐like growth factor 1 (IGF1) signaling might increase risk factors for Alzheimer's disease (AD)." (PMID 38361318, 2024). "Furthermore, the accumulation of visceral obesity leads to insulin resistance, resulting in elevated levels of insulin and IGF-1, both of which further contribute to the risk of developing prostate cancer." (PMID 38214779, 2024). "A Korean study found that a combination of anaerobic and aerobic exercise improves insulin resistance and promotes the secretion of hormones associated with aging, such as the growth hormone (GH), insulin-like growth factor 1 (IGF-1), and dehydroepiandrosterone sulfate (DHEA-S), in older women." (PMID 39518709, 2024). "Additionally, obesity is often associated with insulin resistance and elevated levels of insulin-like growth factor 1 (IGF-1), both of which have been implicated in the pathogenesis of acne." (PMID 38556870, 2024). "Additionally, insulin resistance and associated neuroinflammation have also been involved in the development of PD, possibly through the insulin-like growth factor 1 (IGF-1) signaling pathway." (PMID 38219272, 2024). "We hypothesize that insulin resistance and increased IGF-1 concentrations predispose to postprandial insulinemic spikes and are related to fat accumulation in adipocytes." (PMID 36915133, 2023). "Moreover, obesity is closely linked to insulin resistance and hyperinsulinemia, which lead to increased IGF-1 levels, activating the PI3K/AKT/mTOR pathway, which is frequently dysregulated in HCC." (PMID 37834153, 2023). "Insulin resistance in the brain is accompanied by insulin-like growth factor-1 (IGF-1) resistance and may be associated with insulin receptor substrate-1 dysfunction." (PMID 37962457, 2023). "IGF-1 is involved in the pathological process of retinal degeneration and may be associated with the microglia-mediated inflammatory response and insulin resistance." (PMID 37358957, 2023). "It had been reported that reduced physical activity, insulin resistance, growth hormone/insulin-like growth factor (GH/IGF-1) axis, vitamin D3 deficiency, and chronic inflammation have been recognized as mediators of mutual interactions between the skeleton and the liver." (PMID 39263527, 2023). "In addition, muscle loss leads to insulin resistance and increases the activity of IGF-1, which can regulate hepatocyte proliferation." (PMID 36923698, 2023). "The possible role of insulin resistance and IGF-1 in the association between PCOS and EC is supported by observations that endometrial dysfunction, causing miscarriages in PCOS, has been linked to insulin resistance and the associated elevation in serum IGF-1 levels in individuals with PCOS." (PMID 37988160, 2023). "While both high and low IGF‐1 level may be associated with glucose intolerance and insulin resistance (U‐shaped effect), there are positive correlation between IGFBP3 (IGF‐binding protein 3) and glucose intolerance/insulin resistance." (PMID 37143466, 2023).
Insulin resistance (continued). "Furthermore, aging promotes TN formation with the risk of associated metabolic syndrome, insulin resistance and high levels of insulin-like growth factor-1." (PMID 36874270, 2023). "Insulin resistance may be an indirect cause of the lower IGF-1 levels observed in patients with OSAHS." (PMID 36120463, 2022). "Insulin resistance can cause renal injury through renin-angiotensin system activation, increases in aldosterone and angiotensin II with subsequent effects on endothelin-1 and insulin-like growth factor-1, and the generation of reactive oxygen species." (PMID 35885048, 2022). "Furthermore, the metabolic syndrome that accompanies obesity is associated with insulin resistance, hyperinsulinemia, increased synthesis of insulin-like growth factor 1 (IGF-1)." (PMID 35626173, 2022). "Furthermore, GH causes insulin resistance and pubertal insulin resistance positively correlates with GH and IGF1 levels." (PMID 36107617, 2022). "Insulin receptor activity (tyrosine kinase) also decreases simultaneously, leading to structural or functional defects in various enzymes in the glucose metabolic pathway (e.g., glucokinase) and impaired glucose metabolism in the body, which results in insulin resistance and IGF-1 deficiency." (PMID 36120463, 2022). "Obesity causes insulin resistance, which is associated with prolonged hyperinsulinemia and increased circulating IGF1, which could exert neoplastic activity by promoting cell cycle progression and inhibiting apoptosis." (PMID 35207622, 2022). "However, a meta-analysis of 76,558 non-diabetic populations of European descent found that the G allele at IGF1 rs35767 was associated with increased fasting insulin levels and insulin resistance (HOMA-IR)." (PMID 35094288, 2022). "Insulin resistance, highly prevalent among overweight and obese adolescents and adults, is positively correlated with insulin-like growth factor-1 (IGF-1), an established breast mitogen positively associated with mammographic breast density and breast cancer risk among premenopausal women." (PMID 34998441, 2022). "The mechanism underlying the relationship between obesity-linked CRC risk is that obesity promotes insulin resistance or hyperinsulinemia, chronic inflammation, oxidative stress, DNA damage, and elevated insulin-like growth factor-1 (IGF-1) levels, stimulating cell proliferation." (PMID 35406504, 2022). "Reduced levels of IGF-1(insulin-like growth factor) and insulin resistance may result in reduced IGF-1 and insulin brain uptake, causing β-amyloid accumulation." (PMID 35269827, 2022). "However, overexpression of IGF-1 caused insulin resistance in the brain and promoted the hyperphosphorylation of tau protein and the accumulation of amyloidosis, which will eventually lead to synaptic apoptosis." (PMID 34659078, 2021). "Insulin resistance was found to be associated with IGF-1 levels in insulin resistant SMA patients." (PMID 34371910, 2021). "Obesity may increase BC risk through multiple mechanisms including insulin-resistance, metabolic syndrome, increased production of sex hormones and insulin-like growth factor-1 (IGF-1)." (PMID 34706754, 2021). "Insulin resistance and alterations in IGF-1 and IGF-2 have been implicated in MDD and may explain the three- to four-fold increase in depression in patients with diabetes." (PMID 34335334, 2021). "In addition, osteoporosis and sarcopenia shared common underlying mechanisms, including insulin resistance, decreased anabolic hormones, such as IGF-1 and testosterone, increased inflammatory cytokines, including IL-1, IL-6, and TNF-α, as well as dysbiosis." (PMID 33807573, 2021). "Additionally, this inflammatory state causes insulin resistance which translates into a state of hyperglycemia, hyperinsulinemia, increased circulating insulin-like growth factor 1 (IGF-1) which have also been recognized to be involved in carcinogenesis." (PMID 32351453, 2020).
Insulin resistance (continued). "On the other hand, high levels of IGF-1 such as observed in acromegaly are associated with profound insulin resistance, which may offset the beneficial (micro)vascular effects of IGF-1." (PMID 33633687, 2020). "In addition, chronic hyperinsulinemia with associated insulin resistance has a key role in the etiology of BC as it induces the production of IGF-1, which is capable of causing mutagenic changes." (PMID 32630215, 2020). "The likely mechanism explained for this increased risk of carcinogenesis is related to the simultaneous increase in both the insulin-like growth factor-1 (IGF-1) levels and insulin signaling pathways, which causes hyperglycemia, insulin resistance, and hyperinsulinemia." (PMID 32742851, 2020). "Regarding insulin-resistance, the associated hyperinsulinemia directly increases cardiac mass and left ventricle dysfunction, through the interaction between insulin, its receptor and insulin-like growth factor-1 (IGF-1) receptor, expressed in the myocardium." (PMID 32033349, 2020). "Conversely, lower IGF-1 quartiles were associated with higher blood glucose and insulin resistance." (PMID 32806629, 2020). "Consequently, low and sub-physiological circulating IGF-1 levels are associated with an increased prevalence of CVD risk factors such as insulin resistance, hypertension, and with premature atherosclerosis, overt CVD and CVD-related and all-risk mortality." (PMID 32458292, 2020). "This suggests that elevated IGF-1 levels may increase the risk of type 2 diabetes in part through insulin resistance." (PMID 32548700, 2020). "High IGF-1 levels could increase insulin sensitivity, while insulin resistance has been associated with lower IGF-1 and enhanced metabolism of HDL particles by hepatic lipase." (PMID 33101407, 2020). "Moreover, brain insulin resistance is associated with IGF-1 resistance, and these defects contribute to the cognitive decline in patients with Alzheimer’s disease." (PMID 31939479, 2019). "Insulin resistance and suppressed IGF-1 signaling drive the loss of muscle mass." (PMID 31013777, 2019). "Both low and high levels of IGF-1 have also been associated with insulin resistance." (PMID 31998361, 2019). "Briefly, increased adiposity among breast cancer survivors has been positively correlated with insulin resistance as well as poorer regulation of insulin growth factor-1 (IGF-1) and estrogen—two hormones frequently implicated in breast cancer development and recurrence." (PMID 29880779, 2018). "Insulin resistance is associated with increased insulin-like growth factor I (IGF-1)." (PMID 29587682, 2018). "Thus, GH deficiency is paradoxically associated with insulin resistance and abdominal obesity, a phenomenon possibly attributed to decreased IGF1 activity." (PMID 30287811, 2018). "This could potentially be explained by hyperglycaemia being a symptom of hyperinsulinaemia (as a consequence of insulin resistance), and perhaps a stronger association would be have been found if IGF-1 were investigated directly." (PMID 28376727, 2017). "Additionally, in obesity there are elevated levels of growth hormones (i. e. insulin and insulin like growth factor-1) as a consequence of the insulin resistance, which is also causally linked to dysfunctional adipose tissues, especially VATs." (PMID 28886117, 2017). "As both insulin resistance and IGF-1 are linked to increased cancer risk, it is conceivable that myo-Ins modulation of insulin activity may efficiently contribute to reducing cancer risk." (PMID 27795708, 2016). "The positive relationship between T2DM and CRA may be linked to insulin resistance or an increased insulin-like growth factor 1 (IGF-1) might take effect in the adenoma–carcinoma process." (PMID 27535548, 2016).
Insulin resistance (continued). "Sustained or excess GH secretion is associated with insulin resistance in both physiological (in healthy individuals during exercise and sleep) and pathological (acromegaly) states, while the association between IGF-1 and insulin resistance is complex and remains less well understood." (PMID 26906713, 2016). "Given that myo-Ins may efficiently counteract insulin resistance and its metabolic complications, it is tempting to speculate that it may also prevent IGF-1 increase associated with insulin resistance." (PMID 27795708, 2016). "Previously it has been reported that aging rats showed low IGF-1 circulating levels associated to hyperlipidemia (cholesterol and triglycerides), hyperglycemia with insulin resistance, as well as an increase of peroxidative liver damage and mitochondrial dysfunction." (PMID 26467524, 2015). "Obese patients have been shown to have higher circulating levels of IGF-1 than non-obese patients in the presence of hyperinsulinemia, and animal studies have revealed that insulin resistance and activation of the IGF/IGF-1R axis are implicated in obesity- and diabetes-related liver carcinogenesis." (PMID 25789501, 2015). "IGF-1 levels have been associated with insulin resistance and hyperglycemia." (PMID 25996963, 2015). "Insulin levels, the HOMA-IR index, total IGF-1 levels and increased insulin resistance are positively associated with CIMT; simultaneously, insulin resistance in obese adolescents can impair changes in CIMT and can lead to the early development of atherosclerosis." (PMID 26666335, 2015). "Deletion of ALS ameliorated the insulin resistance that develops in the IGF-1-deficient (LID) mice." (PMID 24966876, 2014). "Additionally, low serum IGF-1 level was associated with insulin resistance and poor overall survival in HCC patients." (PMID 24586785, 2014). "The peptide hormone insulin is produced by beta cells in the pancreas and released in response to hyperglycemia, which is associated with insulin resistance, aberrant glucose metabolism, chronic inflammation, and the production of other metabolic hormones, such as IGF-1, leptin, and adiponectin." (PMID 24280167, 2013). "Insulin resistance is becoming increasingly common and one of the potential mechanisms through which insulin resistance affects cancer risk is through an increase in the bioavailability of IGF-1." (PMID 23434903, 2013). "Furthermore, IGF-1 resistance has recently been demonstrated to be associated with brain insulin resistance and cognitive decline in Alzheimer’s patients." (PMID 24252636, 2013). "In genome-wide association studies (GWAS), single-nucleotide polymorphisms (SNPs) around IGF1 have been associated with height and the C allele of rs35767 upstream of the gene has been associated with increased fasting insulin and insulin resistance risk as well as lower levels of IGF-I." (PMID 22253814, 2012). "Diabetes might increase the risk of kidney cancer by hyperinsulinemia and insulin resistance, higher IGF-1 in serum and hypertension." (PMID 22839452, 2012). "Further, because of their increased risk of development of insulin resistance in adulthood, we hypothesized that these alterations of IGF-1 will be worse in males." (PMID 22548154, 2012). "When untreated, primary IGF-1 deficiency may lead to a range of metabolic disorders, including lipid abnormalities, insulin resistance, and decreased bone density." (PMID 20200935, 2010). "We hypothesize that people with insulin resistance are at risk of developing cancer due to high levels of circulating IGF-1." (PMID 17953765, 2007). "Notably, elevated IGF-1 levels have been associated with insulin resistance, and this complex interplay may contribute to the pathogenesis of DM2." (PMID 39273161, 2024).
Insulin resistance (continued). "Our data show that higher levels of IGF-1 were predisposed to significantly greater improvements in intrahepatic lipids and in the visceral fat volume, markers which are strongly associated with metabolic syndrome, insulin resistance, and diabetes risk despite comparable weight loss." (PMID 38928106, 2024). "Furthermore, an increase in insulin resistance was associated with a decrease in IGF-1 levels." (PMID 39578883, 2024). "Moreover, lower IGF-1 concentrations have been found to be associated with the presence of traditional vascular risk factors, particularly obesity, insulin resistance, and diabetes mellitus, which might be feasible explanation for brain atrophy." (PMID 37608387, 2023). "We found that MOL supplementation markedly decreased the body weight, significantly upregulated the expression of Sirt1, FoxO1, PGC‐1α, IGF1, and substantially modulated the sex hormone level and improved insulin resistance, which may be associated with the relieves oxidative stress." (PMID 37701184, 2023). "In addition, cancer cell mitosis could be promoted by hyperinsulinemia caused by insulin resistance through molecules such as insulin receptor-A and insulin-like growth factor-1 (IGF-1), and high glucose could activate the IGF-1 receptor signaling pathway." (PMID 37122334, 2023). "In addition, the production of growth hormone and insulin-like growth factor-1 increases during puberty, and both have been linked to insulin resistance during puberty, pointing to the possibility that they may contribute to the association found." (PMID 37079135, 2023). "Moreover, VAT is associated with insulin resistance, characterized by elevation of both insulin-like growth factor-1 (IGF-1) and insulin levels, associated with an increased autophagy, which promoted HepG2 cell survival and metastasis, leading to a worse prognosis for HCC patients." (PMID 36358709, 2022). "Thus, the dysregulation of serum IGF-1 caused by vitamin C deficiency shown in our study may explain the increased insulin resistance in vitamin C deficient Gulo (−/−) mice presented in the previous report." (PMID 34221500, 2021). "Additionally, hyperinsulinemia caused by insulin resistance could promote cancer cell mitosis through molecules such as insulin receptor-A and insulin-like growth factor-1, or through activation of the insulin-like growth factor-1 receptor signaling pathway." (PMID 34604147, 2021). "It is possible that insulin resistance may cause changes in proliferative pathways activated directly by insulin or insulin-like growth factor-1 (IGF-1), which helps regulate thyroid gene expression and may be important in thyrocyte proliferation and differentiation." (PMID 29374470, 2018). "This increase could be due to an increase in adiposity as of this age (and fat inhibiting the effect of insulin), or a progressive increase in insulin-like growth factor-1 that takes place as puberty approaches and has effects associated with insulin resistance." (PMID 29402762, 2018). "Obesity is characterized by increased fat mass, insulin resistance, hyperinsulinemia, and an increased risk not only for type 2 diabetes but also for cancer; acromegaly is also characterized by insulin resistance but with decreased fat mass, and an excess of GH, insulin, and IGF1." (PMID 28316059, 2017). "Considering insulin resistance is deeply associated with L-asp-related hyperglycemia, the limitation of this study is that we could not evaluate serum biomarker of insulin resistance such as leptin, adiponectin, GH and IGF1." (PMID 26317422, 2015). "In vivo IRS-2-deficient mice, a model of insulin resistance and type 2 diabetes, displayed tau-hyperphosphorylation and developed intracellular deposits of hyperphosphorylated tau during aging suggesting a critical role for IR/IGF-1 signaling in regulation of tau phosphorylation in vivo." (PMID 22654904, 2012).